NLRP6 (NLR family pyrin domain containing 6)
Description:
Acts as the sensor component of the NLRP6 inflammasome, which mediates inflammasome activation in response to various pathogen-associated signals, leading to maturation and secretion of IL1B and IL18. Inflammasomes are supramolecular complexes that assemble in the cytosol in response to pathogens and other damage-associated signals and play critical roles in innate immunity and inflammation. Acts as a recognition receptor (PRR): recognizes and binds specific pathogens and other damage-associated signals, such as lipoteichoic acid (LTA), a cell-wall component of Gram-positive bacteria, or double stranded RNA (dsRNA). May also recognize and bind lipopolysaccharide (LPS), a major component of the outer membrane of Gram-negative bacteria; however, LPS is probably not a major activator of the NLRP6 inflammasome. Following LTA- or dsRNA-binding, NLRP6 undergoes liquid-liquid phase separation (LLPS), enhancing multivalent interactions, an essential step for the formation of the NLRP6 inflammasome polymeric complex. The NLRP6 inflammasome acts by promoting recruitment of effector pro-inflammatory caspases (CASP1 and/or CASP4) that catalyze maturation and secretion of IL1B and IL18 in the extracellular milieu. The NLRP6 inflammasome plays a central role in the maintenance of epithelial integrity and host defense against microbial infections in the intestine. Required to restrict infection against Gram-positive bacteria by recognizing lipoteichoic acid (LTA), leading to recruitment of CASP4 and CASP1, and subsequent maturation and secretion of IL1B and IL18. Involved in intestinal antiviral innate immunity together with DHX15: recognizes and binds viral dsRNA to restrict infection by enteric viruses through the interferon pathway and GSDMD-dependent release of IL18. Required to prevent infection by the apicomplexan parasite Cryptosporidium in enterocytes by promoting GSDMD-dependent release of IL18 (By similarity). The NLRP6 inflammasome may also regulate the gut microbiota composition by acting as a sensor of microbiota-associated metabolites to form a PYCARD/ASC-dependent inflammasome for downstream IL18 release and secretion of antimicrobial peptides (By similarity). Essential for gut mucosal self-renewal and proliferation (By similarity). Regulate mucus secretion in an inflammasome- and autophagy-dependent manner to prevent invasion by enteric bacteria, (By similarity). During systemic bacterial infections, the NLRP6 inflammasome negatively regulates neutrophil recruitment and neutrophil extracellular traps (NETs) formation (By similarity). May promote peripheral nerve recovery following injury via an inflammasome-independent mechanism (By similarity).
Synonyms: NALP6; PYPAF5; PAN3; CLR11.4; AVR; NAVR; NAVR/AVR
Tractability: Antibody: UniProt places it where antibodies can reach, with medium confidence; its Gene Ontology location is reachable by antibodies, with medium confidence. PROTAC: UniProt records ubiquitination sites on it.
Gene: Protein-coding gene on chromosome 11 (278,407 to 285,388, forward strand). Ensembl gene ENSG00000174885.
Subcellular location: Cytoplasm, cytosol; Inflammasome; Cell membrane; Nucleus membrane
Gene Ontology:
Molecular function: lipopolysaccharide binding; lipoteichoic acid binding; molecular condensate scaffold activity; pattern recognition receptor activity; signaling adaptor activity; peptide binding; vasopressin receptor activity; signaling receptor activity
Biological process: antiviral innate immune response; defense response to Gram-positive bacterium; defense response to virus; NLRP6 inflammasome complex assembly; positive regulation of inflammatory response; positive regulation of interleukin-18-mediated signaling pathway; protein homooligomerization; acute inflammatory response; regulation of inflammatory response; G protein-coupled receptor signaling pathway; host-mediated modulation of intestinal microbiota composition; negative regulation of canonical NF-kappaB signal transduction; negative regulation of ERK1 and ERK2 cascade; negative regulation of inflammatory response to antigenic stimulus; pyroptotic inflammatory response; signal transduction
Cellular component: canonical inflammasome complex; cytosol; membraneless organelle; NLRP6 inflammasome complex; cytoplasm; nuclear membrane; plasma membrane
Genetic constraint (gnomAD): Loss-of-function variants: 55 observed, 55.71 expected, observed/expected ratio (o/e) 0.99, 90% interval 0.79 to 1.24. The synonymous counts are far from expectation, so gnomAD's model fits this gene poorly and the ratio says little. Missense variants: 1,238 observed, 1,097.5 expected, observed/expected ratio (o/e) 1.13, 90% interval 1.08 to 1.18. Synonymous variants: 652 observed, 522.03 expected, observed/expected ratio (o/e) 1.25, 90% interval 1.17 to 1.33.
Homologues: Orthologues: chimpanzee NLRP6 (99% identical), macaque NLRP6 (95% identical), pig NLRP6 (74% identical), dog NLRP6 (74% identical), rat Nlrp6 (71% identical), mouse Nlrp6 (69% identical). Paralogues in human: NLRP3 (27% identical), NLRP12 (26% identical), NLRP1 (22% identical), NLRP4 (21% identical), NLRP7 (21% identical), NLRP14 (20% identical), NLRP9 (20% identical), NLRP2 (20% identical), CIITA (19% identical), NLRP8 (19% identical), NLRP5 (19% identical), NOD1 (18% identical), and 8 more.
Diseases named in the same sentence as NLRP6 in open-access papers:
NLRP6 is named in the same sentence as 137 diseases in open-access papers, as found by Europe PMC text mining. Sharing a sentence is not in itself a finding about the gene and the disease. The quoted sentences say what the papers report.
colitis (102 papers, 2013 to 2026). Inflammation of the colon. "Although A. muciniphila has been associated with improvements in local and systemic inflammation, Nlrp6-deficient mice are more susceptible to colitis due to an increase in A. muciniphila in the gut." (PMID 38315242, 2024). "The red cluster is primarily associated with inflammatory bowel diseases (colitis and Crohn’s disease), the immune system, and NLRP6 inflammasome." (PMID 39834371, 2024). "Studies involving fecal transplantation and co-housing have demonstrated that NLRP6-deficient mice can transmit both cancer and colitis susceptibility to wild-type animals." (PMID 38248332, 2024). "In this line, Nlrp6-deficient mice showed dysbiosis conferring increased susceptibility to colitis, colitis-associated colorectal cancer and metabolic syndrome development." (PMID 38315242, 2024). "Another study found that the abundance of A. muciniphila increased significantly in the mouse intestines after worsening of spontaneous colitis caused by NLRP6 gene knockout in IL-10−/− mice, and that A. muciniphila administration orally worsened the colitis." (PMID 36937258, 2023). "NLRP6-knockout mice appear to be more susceptible to DSS-induced colitis than wild-type (WT) mice, possibly due to defective autophagy and reduced mucus secretion in goblet cells." (PMID 36016685, 2022). "In this regard, the upregulation of Nlrp6 in infiltrating monocytes after DSS-induced colitis reduces the susceptibility to chemically induced intestinal injury by restoring the intestinal barrier and limiting the induction of bacteria-driven inflammation." (PMID 35650327, 2022). "Mice deficient for either TLR2, 4, 5, and 9, the TLR-pathway mediator MyD88 or the NLRP6 inflammasome are highly susceptible to experimentally induced colitis." (PMID 33538854, 2021). "Deletion of Nlrp6 aggravates DSS-induced colitis or colitis-associated tumor growth due to deregulated regeneration and proliferation of intestinal epithelial cells." (PMID 33910012, 2021). "Intestinal hyperplasia, inflammatory cell migration and an increase in the severity of DSS-induced colitis were some of the characteristics of NLRP6-deficient mice." (PMID 34571825, 2021). "Our results show that Cyld deficiency resulted in severe colitis, which was associated with an increased level of NLRP6 inflammasome activity and IL-18 in the colonic mucosa." (PMID 33910012, 2021). "Studies have discovered that NLRP6 plays a role in protecting against experimental colitis and colitis-associated cancer and monocytes." (PMID 34571825, 2021). "Mice showed protection against colitis when cohoused with apigenin‐treated mice, whereas NLRP6‐deficient mice lost the protective effect." (PMID 33682108, 2021). "In further studies they found that NLRP6 plays a role in inhibiting the spontaneous colitis in IL-10 deficient mice, probably by inducing the enrichment of Akkermansia muciniphila, a bacterium that can promote development of colitis." (PMID 33808793, 2021). "WT mice co-housed with these inflammasome KO mice developed a more severe DSS-induced colitis than single-housed WT, and this effect was attributed to the horizontal transfer of colitogenic microbiota derived from the Nlrp6- or ASC-deficient mice to WT mice." (PMID 33143375, 2020). "Adoptive transfer of Ly6Chi monocytes from wildtype mice to Nlrp6 deficient mice resulted in protection from colitis, a reduction in barrier permeability, lower bacterial translocation, and increased survival." (PMID 33036374, 2020). "NLRP6-deficient mice are more susceptible to intestinal inflammation and to chemically induced colitis due to the important role of NLRP6 for mucosal self-renewal and proliferation." (PMID 29570694, 2018). "NLRP6 KO mice were found to have different microbiota configuration which make them more susceptible to chemical-induced colitis compared to the WT mice." (PMID 30248149, 2018).
colitis (continued). "NLRP6 is an important protector against colitis and colitis-associated tumorigenesis, but few reports have examined the involvement of NLRP6 in gastric cancer." (PMID 29340077, 2017). "Prior reports have demonstrated that NLRP6 promotes intestinal homeostasis and protects against the development of colitis and colitis-associated tumorigenesis in mice." (PMID 29340077, 2017). "NLRP6, a member of the Nod-like receptor family, protects against chemically induced intestinal injury and colitis-associated colon cancer." (PMID 29340077, 2017). "Deficiency in NLRP6 and IL-18 has also been linked to colitis-related colorectal cancer (CRC) development." (PMID 26925061, 2016). "Co-housing of Nlrp6-deficient mice with wild-type mice resulted in dysbiotic microbial transfer to the recipient wild-type mice and exacerbation of colitis, cancer, hepatic steatosis, and obesity in the new host." (PMID 26589591, 2015). "Mice with either chemically induced colitis or genetic mutations, like NLRP6 or TRUC mice that produce colitis, have a greatly altered intestinal microbiome." (PMID 24416190, 2014). "NLRP6 deficient mice develop sever colitis in response to DSS when compared to wild type mice, manifested with reduced IL-18 expression by IECs and increased pathology." (PMID 24886810, 2014). "Reduced expression of IL-18 was observed in NLRP6 deficient mice, as well as increased susceptibility to chemically induced colitis." (PMID 25071778, 2014). "These mice deficient in NLRP6 develop a colitis phenotype, and this is transmissible to cohoused wild-type mice, both early in postnatal life and during adulthood." (PMID 23606794, 2013). "In other studies, Nlrp6 deficiency predisposes mice to increased inflammation in models of colitis and to increased tumorigenesis in colon cancer models." (PMID 24062750, 2013). "The characteristic alteration of NLRP6 deficiency in mouse colonic epithelial cells is that exposure to DSS worsens colitis, and the resultant increased abundance of phylum Bacteroidetes (Prevotellaceae) can produce DSS-induced colitis by inducing CCL5 in neonatal or adult wild-type mice." (PMID 37389342, 2023). "In addition, NLRP6-deficient mice are more susceptible to chemically induced colitis due to a compromised mucosal barrier." (PMID 36016685, 2022). "It has been previously shown that transfer of Prevotella-rich dysbiotic gut microbiota from Asc knockout or NLRP6 knockout mice to wild-type mice induced experimental colitis characterized by increased weight loss, tissue pathology, and death in recipient mice." (PMID 36275026, 2022). "Interestingly, co-housing of Nlrp6−/− mice transferred microbiota to WT mice, resulting in enhanced susceptibility of WT mice to colitis." (PMID 33910012, 2021). "Similarly, Seregin and colleagues showed that deficiency in NLRP6 increases the susceptibility to colitis in Il10−/− mice." (PMID 34705319, 2021). "Of note, the transfer of the dysbiotic microbiota from Nlrp6‐deficient mice to WT mice confers susceptibility to DSS‐induced colitis, suggesting that NLRP6 may be crucial for the fine‐tuning of the gut microbiota." (PMID 34705319, 2021). "Similar as in the case of TLRs, murine NLR knock-out models (Nod2, Nlrp3, Nlrp6, Nlrc4, caspase 1) with increased (albeit partly controversial) susceptibility in different colitis models point to NLRs as important host factors for the establishment of a protective gut microbiota." (PMID 33117398, 2020). "Indeed, the loss of NLRP6 favors colitis through microbiome dysregulation and a defect in the mucus protective function." (PMID 33255437, 2020). "In addition, higher proportion of Prevotellaceae has been detected in the microbiota of NLRP6 KO mice with high risk for colitis." (PMID 33324697, 2020). "Moreover, NLRP6-deficiency causes an enrichment of A. muciniphila population, which can act as a pathobiont to promote colitis in a genetically susceptible host." (PMID 31510015, 2019).
colitis (continued). "Interestingly, deficiency in the NLRP6 inflammasome is detrimental in DSS-induced colitis, in a manner related to insufficient IL-18." (PMID 31139196, 2019). "Additionally, Nlrp6 and Nlrp3 have been shown to negatively regulate colitis-associated tumorigenesis." (PMID 29120406, 2017). "Our results are consistent with the previous studies showing correlation between the increase in the abundance of Prevotellaceae and the severity of microflora-transmissible colitis in NLRP6 inflammasome-deficient mice, in IL22-/- mice, and in Casp3/11-/- mice." (PMID 26727498, 2016). "Nlrp6 regulates the goblet mucus secretion, and self-renewal of the intestinal epithelium and its deficiency leads to aberrant wound healing, promoting colitis-associated colon carcinogenesis." (PMID 26253422, 2015). "Moreover, whereas the NLRP6 inflammasome subtype regulated colonic microbial ecology and risk for colitis, it was also shown to be involved in control of epithelial self-renewal and colorectal carcinogenesis upon injury." (PMID 26355424, 2015). "In agreement with the findings in Casp1−/− mice, NLRP6-deficient mice had impaired IL-18 production mainly from the intestinal epithelial compartment further diminishing the capacity of these mice to recover from colitis." (PMID 25071785, 2014). "Thus, NLRP3 and NLRP6 appear to have a specific protective role within the gastrointestinal tract through production of IL-18, and accordingly, NLRP3−/− and NLRP6−/− mice are more susceptible to colon inflammation and colon cancer." (PMID 24367371, 2013). "However, the mechanisms proposed for susceptibility to colitis and tumorigenesis are reportedly due to NLRP6 mediated inflammasome activation." (PMID 24062750, 2013). "Components of the Nlrp6 inflammasome are expressed in intestinal epithelial cells and throughout the intestinal tract, and several studies have demonstrated a protective role of Nlrp6 against colitis and colitis-associated tumor formation [reviewed in Ref." (PMID 24409180, 2013). "However, in comparison to mice deficient for Nlrp3, Nlrp10, Nlrp12, and Nlrc4, Nlrp6 showed the largest potential to alter microbiota and colitis susceptibility of co-housed mice." (PMID 24409180, 2013). "Additionally, NLRP6 deficiency has been linked to intestinal inflammation, hyperplasia, and worsened colitis in mice, suggesting that disruptions in the inflammasome pathway may increase susceptibility to IBD." (PMID 40426715, 2025). "Interestingly, investigations involving bone marrow chimeras have revealed that while colitis severity appears to be associated with NLRP6 function in the epithelial cell compartment, higher carcinogenesis in NLRP6-deficient mice has been associated with the hematopoietic cell compartment." (PMID 38248332, 2024). "Intriguingly, one study reported that housing wild-type mice and NLRP6-deficient mice together enhanced disease severity in wild-type mice, which was interpreted as evidence that microbiota can act as a driving factor of enhanced colitis in an NLRP6-dependent manner." (PMID 38177104, 2024). "Moreover, NLRP6 deficiencies predisposed the host to colitis-associated tumor growth." (PMID 39684769, 2024). "Interestingly, colitis and carcinogenesis susceptibility with NLRP6, ASC or IL-18-deficient mice could be transferred to naive wild-type mice by cross-fostering and cohousing the mice together, leading to a dysbiotic gut microbiota." (PMID 34571825, 2021). "Nlrp6−/− mice have an altered gut microbiome, including the expansion of two colitis-inducing pathobionts, the Prevotellaceae family and Akkermansia muciniphila, and are more susceptible to DSS-induced colitis and tumorigenesis." (PMID 41062723, 2025). "Histamine produced by microbiota dysbiosis in the colon suppresses NLRP6 inflammasome assembly, IL-18, and its downstream anti-microbial peptide expression, thus exacerbating dextran sodium sulfate-induced colitis." (PMID 38791713, 2024).